FOXA1 (forkhead box A1)
Diseases named in the same sentence as FOXA1 in open-access papers (continued):
Sharing a sentence is not in itself a finding about the gene and the disease.
metastatic prostate carcinoma (3 papers, 2018 to 2022). A carcinoma that arises from the prostate gland and has spread to other anatomic sites. "We sequenced the untranslated regions (UTRs) of 72 established driver genes in 428 patients with metastatic prostate cancer and identified FOXA1 3′-UTR mutations in 12% of patients." (PMID 30272002, 2018). "Here, we show that FOXA1 functions as the primary orchestrator of alternative splicing dysregulation across 500 primary and metastatic prostate cancer transcriptomes." (PMID 36170835, 2022).
mucinous adenocarcinoma (3 papers, 2018 to 2020). An invasive adenocarcinoma composed of malignant glandular cells which contain intracytoplasmic mucin. "Histopathologic analysis of controls showed that the lungs contained mucinous adenocarcinoma that expressed HNF4α and the expected pattern of FoxA1/2." (PMID 30475207, 2018).
upper tract urothelial carcinoma (3 papers, 2017 to 2024). "GATA binding protein 3 (GATA3) and forkhead box A1 (FOXA1) have been individually implicated in the progression of upper tract urothelial carcinoma (UTUC)." (PMID 38425344, 2024). "Tumor samples from 222 patients with upper tract urothelial carcinomas who were treated with radical nephroureterectomy were analyzed for the expression of seven basal/luminal immunohistochemical markers (CK5, EGFR, CD44, CK20, p63, GATA3, FOXA1)." (PMID 28632777, 2017).
adenoma (2 papers, 2019 to 2025). A neoplasm arising from the epithelium. "Therefore, the following scenario appears likely: During the initiation of early adenomas, the expression of FOXA1 and consequently RBM47 is decreased." (PMID 41335176, 2025). "During adenoma to carcinoma progression the RBM47 promoter becomes increasingly hypermethylated, suggesting that the initial downregulation of RBM47, at least in part, due to the down-regulation of FOXA1 is epigenetically fixed." (PMID 41335176, 2025).
Alzheimer disease (2 papers, 2020). A progressive, neurodegenerative disease characterized by loss of function and death of nerve cells in several areas of the brain leading to loss of cognitive function such as memory and language. "In Alzheimer’s Disease models based on NGF-stimulated PC12 cells and primary cerebral cortex neurons, MALAT1 inhibits neuron apoptosis and neuroinflammation, while it stimulates neurite outgrowth via miR-125b-regulated PGTS2, CKD5, and FOXA1 expression." (PMID 33192306, 2020).
bladder urothelial cancer (2 papers, 2016 to 2022). "More recently, FOXA1 was found to upregulate and high FOXA1 expression have lower rates of progression free survival in Urothelial carcinoma of the bladder." (PMID 26909612, 2016).
Cirrhosis (2 papers, 2012 to 2024). A chronic disorder of the liver in which liver tissue becomes scarred and is partially replaced by regenerative nodules and fibrotic tissue resulting in loss of liver function. "Notably, the expression of FOXA1, GSTZ1, WDR72 and UHMK1 was more upregulated in the tissues of individuals with hepatic cirrhosis than those with liver failure, although statistical significance was not achieved." (PMID 38287425, 2024). "Furthermore, the liver tissues of patients with liver failure and hepatic cirrhosis exhibited downregulated expression of CBS, CYP1A2, FOXA1, GSTZ1, WDR72 and UHMK1 when compared to healthy controls." (PMID 38287425, 2024).
colon adenocarcinoma (2 papers, 2019 to 2025). "FOXA1, which plays a central role in various biological processes such as organogenesis, differentiation, glycolipid metabolism, proliferation, migration, and invasion, has been reported to be highly expressed in normal human colon tissue but downregulated in colon adenocarcinoma." (PMID 40870875, 2025).
colorectal tumors (2 papers, 2023 to 2025). "Since our results implied that the down-regulation of FOXA1 and RBM47 expression promotes tumor progression, FOXA1 and RBM47 expression in different stages of colorectal tumors was analyzed." (PMID 41335176, 2025). "Indeed, FOXA1 and RBM47 expression progressively decreased from stage 1 to stage 4 colorectal tumors in the majority of analyzed CRC patient cohorts." (PMID 41335176, 2025).
COVID-19 (2 papers, 2021 to 2022). A disease caused by infection with severe acute respiratory syndrome coronavirus 2. "The FOXA1 transcription factor network (HNF3A pathway M285) BP with overrepresented proteins in response to COVID-19 increased in enrichment with disease severity." (PMID 34566994, 2021).
diabetes insipidus (2 papers, 2012 to 2025). A disorder characterized by excretion of large amounts of urine, accompanied by excessive thirst. "Hence, Foxa1, but not Foxa2, is expressed in the kidney and, when deleted, causes nephrogenic diabetes insipidus." (PMID 22737085, 2012).
ductal adenocarcinoma (2 papers, 2021 to 2024). "In ductal adenocarcinoma of the breast, FOXA1, together with EP300 and RUNX1, enhances E-cadherin promoter activity in metastatic breast cancer cells." (PMID 38605023, 2024). "This cell line is representative of estrogen receptor positive (ER+) invasive ductal breast carcinoma, which is known to be mainly driven by the combined activity of the TFs ESR1, GATA3, and FOXA1." (PMID 34174819, 2021).
ductal breast carcinoma (2 papers, 2019 to 2024). "In AR−/FOXA1-cases, the pathological type is mainly ductal carcinoma associated with more central fibrosis and higher grade of ductal carcinoma In situ." (PMID 39777114, 2024).
experimental autoimmune encephalomyelitis (2 papers, 2015 to 2017). An autoimmune demyelinating disease of the central nervous system that is produced experimentally in animals by the injection of homogenized brain or spinal cord in Freund's adjuvant. "We reported previously that neuronal ability to generate FoxA1+Tregs was central to preventing neuroinflammation in experimental autoimmune encephalomyelitis (EAE)." (PMID 28436428, 2017). "In an important article published in Nature Medicine, Liu and colleagues described a novel CD4+ FoxA1+ regulatory T (Treg) cell population as distinct regulators of relapsing-remitting multiple sclerosis (RRMS) and experimental autoimmune encephalomyelitis (EAE)." (PMID 25896927, 2015).
head and neck carcinoma (2 papers, 2018 to 2021). A carcinoma that arises from the head and neck region. "FOXA1 and ESR1, two of the top three ranked factors for head and neck cancer (HNSC) have been identified as tumor suppressors." (PMID 33778495, 2021).
hyperplasia (2 papers, 2016 to 2019). An abnormal increase in the number of cells in an organ or a tissue with consequent enlargement. "Consistent with the role of FOXA1 in regulating the differentiation of prostate epithelial cells, FOXA1 mutations are observed in advanced stage human PCa and inactivation of FOXA1 gene in prostate epithelial cells promotes prostatic hyperplasia in murine models." (PMID 27611945, 2016).
lobular carcinomas (2 papers, 2020 to 2026). "MUCL1 was expressed in 25% of cases in our cohort, enriched in apocrine and lobular carcinomas, and strongly correlated with AR, FOXA1, and GCDFP-15." (PMID 41987297, 2026).
medullary thyroid carcinoma (2 papers, 2015 to 2019). "A similar expression pattern was recapitulated in medullary thyroid carcinoma cells in vivo, consistent with a growth-promoting role of Foxa1." (PMID 26395490, 2015). "Hence, FOXA1 could serve as an additional marker for refining the diagnosis of medullary thyroid carcinoma." (PMID 32372175, 2019).
multiple myeloma (2 papers, 2015). "NF-kB is an important transciption factor as FOXA1 and its critical role is well defined in multiple myeloma." (PMID 25913414, 2015).
neuroendocrine small cell carcinomas (2 papers, 2012 to 2024). "The remaining 2 FOXA1-negative lymph node metastases were dissected from patients diagnosed with stage T3 TCC and small cell carcinoma, both of which were negative for FOXA1 expression." (PMID 22590586, 2012).
osteoporosis (2 papers, 2016 to 2018). A condition of reduced bone mass, with decreased cortical thickness and a decrease in the number and size of the trabeculae of cancellous bone (but normal chemical composition), resulting in increased fracture incidence. "The rs2941742[G] osteoporosis risk allele leads to a near 100-fold decrease in FOXA1 homodimer cooperativity, and causes depressed reporter gene expression." (PMID 29669022, 2018). "Whilst FOXA1, to our knowledge, has not been implicated in osteoporosis, the FOXO group plays an important role in bone metabolism by regulating the redox balance, protein synthesis and differentiation in the osteoblast lineage." (PMID 29669022, 2018). "Interestingly, we found that SNPs influence both FOXA1 and ESR binding in multiple genes, providing a mechanistic link between risk SNPs and osteoporosis." (PMID 26930606, 2016). "It is therefore conceivable that the perturbation of FOXA1 dimers or of related forkhead TFs on the rs2941742 locus modifies ESR1 regulation and contributes to the etiology of osteoporosis." (PMID 29669022, 2018). "FOXA1 and ESR are required for estrogen action in the osteoporosis." (PMID 26930606, 2016).
pancreatic adenocarcinoma (2 papers, 2019 to 2022). "It has been reported that FOXA1 plays an important role as an antagonist of EMT during pancreatic adenocarcinoma progression." (PMID 35804191, 2022).
Pleural effusion (2 papers, 2018 to 2020). The presence of an excessive amount of fluid in the pleural cavity. "In pleural effusion metastases, however, FOXA1 expression is decreased under evolutionary selection pressure of continuous ERα blockade, while GATA3 levels were not affected." (PMID 29972720, 2018). "We chose to focus on pleural effusion metastases (n = 152), due to the large interpatient variation observed in levels of FOXA1 and GATA3 for this metastatic site." (PMID 29972720, 2018). "Also in unpaired analyses, FOXA1 expression in pleural effusions was significantly lower in patients who received adjuvant endocrine therapy compared to the pleural samples of patients who did not receive any adjuvant endocrine treatment (P = 0.021; n = 100; Mann–Whitney U‐test)." (PMID 29972720, 2018).
preeclampsia (2 papers, 2017 to 2022). Preeclampsia is a hypertensive disorder of pregnancy that is characterized by new-onset hypertension with proteinuria presenting after 20 weeks of gestation, and depending on mild or severe forms may initially present with severe headache, visual disturbances, and hyperreflexia. "Downregulation of FOXA1 in the placenta has recently been implicated in early-onset preeclampsia through enhancement of apoptosis and inhibition of migration and invasion of the trophoblastic cells." (PMID 36353514, 2022). "Investigators predicted miR-20a seed-matching sequences in the FOXA1 3’-UTR, and overexpression of miR-20a in human preeclampsia tissue was found to compromise the proliferative and invasive activities of trophoblast cells by repressing the expression of FOXA1 on mRNA and protein level." (PMID 27999212, 2017).
prostatic hyperplasia (2 papers, 2024 to 2025). "Foxa1 genetic ablation causes loss of luminal secretory cells, prostatic hyperplasia and transdifferentiation, in line with an instructing role of Foxa1 in luminal lineage commitment." (PMID 39633177, 2025). "Genomic studies have suggested that FOXA1 regulates the expression of AR and that deletion of FOXA1 in the luminal epithelium of adult mice causes prostatic hyperplasia." (PMID 38778357, 2024). "Additionally, NFIB has been found to interact with FOXA1 as a cofactor in regulating AR target gene expression, and loss of NFIB induces prostatic hyperplasia in a mouse model." (PMID 38778357, 2024).
psoriasis (2 papers, 2022 to 2025). An autoimmune condition characterized by red, well-delineated plaques with silvery scales that are usually on the extensor surfaces and scalp. "In addition, ChIP-seq experiments have identified multiple transcription factor peaks, including AP2-, AP2-, STAT1, STAT3, as well as FOXA1, which has binding sites overlapping with two loci (2q13 for acne and 2q11.2 for psoriasis)." (PMID 39975900, 2025). "NFIC, NFYA, POU2F2, FOXA1 and SRF were discovered to be significant in psoriasis in our study after a gene-transcription factor regulatory network and several relevant transcription factors were evaluated." (PMID 36499614, 2022).
adenosquamous carcinoma of the lung (1 paper, 2018). "In contrast, we observe downregulation of FoxA1/2 expression in the squamous component of both murine and human lung adenosquamous carcinoma." (PMID 30475207, 2018). "FoxA1 and FoxA2 are downregulated in the squamous component of murine and human adenosquamous lung carcinoma." (PMID 30475207, 2018).
Airway obstruction (1 paper, 2014). Obstruction of conducting airways of the lung. "Through another genome wide study, FOXA1 was associated with lung function decline in COPD based on its proximity to the risk loci, and FOXA1 expression was different between the lungs of cases with and without airway obstruction." (PMID 25111050, 2014).
allergic asthma (1 paper, 2026). A asthma with a basis in a pathological type I hypersensitivity reaction. "Within the respiratory system, FOXA1, FOXA2, and FOXA3 have emerged as modulators of pulmonary inflammation, with important implications for the pathogenesis of allergic asthma." (PMID 41868652, 2026).
anaplastic cancer (1 paper, 2021). "Although induction of differentiation may not be expected in anaplastic cancer cells, we found de novo expression of FOXA1 by IHC analysis in GRHL3-expressing T24 cells when incubated in organ culture." (PMID 33803949, 2021).
Autoimmunity (1 paper, 2018). The occurrence of an immune reaction against the organism's own cells or tissues. "It would in the future be interesting to assess the consequences of increased Treg in Foxa1/2Foxn1cKO mice model on induction of autoimmunity and to investigate the clinical significance of the function of FOXA1 and FOXA2 in human TEC." (PMID 30061015, 2018). "Thus, the Foxa1 and Foxa2 transcription factors are important to our understanding of autoimmunity through their roles both in TEC and Treg function." (PMID 30061015, 2018). "Thus, Foxa1 and Foxa2 in TEC promote positive selection of CD4SP T-cells and modulate regulatory T-cell production and activity, of importance to autoimmunity." (PMID 30061015, 2018).
benign breast tumors (1 paper, 2024). "In BC, the gene expression levels and protein expression levels of FOXA1 were significantly higher compared to those in adjacent normal breast tissues and benign breast tumors." (PMID 39440050, 2024).
craniopharyngioma (1 paper, 2025). A benign, partly cystic, epithelial tumor of the sellar region, presumably derived from Rathke pouch epithelium. "FOXA1, FOXJ1, and certain stem cell markers lack in craniopharyngiomas but are expressed in RCCs indicating their potential for pathological diagnosis of RCCs." (PMID 39939491, 2025). "Human RCCs express FOXA1 in a percentage about 94% which is absent in craniopharyngiomas." (PMID 39939491, 2025).
cystic fibrosis (1 paper, 2025). Autosomal recessive disorder caused by pathogenic variants in the CFTR gene (cystic fibrosis transmembrane conductance regulator), which encodes a chloride and bicarbonate channel expressed in epithelial cells, and follow the diagnosis criteria. "The expression of the gene regulating cystic fibrosis transmembrane conductance in intestinal epithelial cells depends on FOXA1/A2." (PMID 40864770, 2025).
Dyskinesia (1 paper, 2016). A movement disorder which consists of effects including diminished voluntary movements and the presence of involuntary movements. "Because of the heavy implication of the STN in etiology and treatment of dyskinesias, we next sought to address the importance of Foxa1 in the adult STN in the modulation of motor behavior." (PMID 27934886, 2016). "Considering the established link between dyskinesias and a compromised state of the STN, we next sought to investigate potential changes in the molecular characteristics of STN neurons following Foxa1 ablation." (PMID 27934886, 2016).
ependymoma (1 paper, 2022). A WHO grade II, slow growing tumor of children and young adults, usually located intraventricularly. "The SHH-2 gene signature comprised ALDH1A2 and EN2, which are involved in the organization of the hindbrain and upregulated in ependymoma PFA2 tumors, as well as the dopaminergic neuron markers FOXA1 and FOXA2." (PMID 35501487, 2022).
follicular carcinomas (1 paper, 2019). "FOXA1 expression was absent as well in all papillary and follicular carcinomas, Hurthle cell carcinoma, and undifferentiated sarcoma." (PMID 32372175, 2019).
homocysteinemia (1 paper, 2016). "Mechanistically, the reduction of Foxa1 expression has been associated with several pathological phenotypic features of NAFLD, including induction of triglyceride synthesis and accumulation, inhibition of fatty acid β-oxidation, and homocysteinemia." (PMID 27103143, 2016).
insomnia (1 paper, 2024). A sleep disorder characterized by difficulty in falling asleep and/or remaining asleep. "We also observed trait-specific patterns of such sequence class enrichment, such as ‘CEBPB-binding site’ (Insomnia: OR = 5.25, p = 0.01) and ‘FOXA1/AR/ESR1-binding site’ (intelligence: OR = 4.69, p = 0.01)." (PMID 38639992, 2024).
Insulin resistance (1 paper, 2012). Increased resistance towards insulin, that is, diminished effectiveness of insulin in reducing blood glucose levels. "NAFL favors insulin resistance and high insulin plasma levels could cause Foxa1 down-regulation." (PMID 22238690, 2012). "Altogether, we suggest that Foxa1 could be a novel therapeutic target for NAFL disease and insulin resistance." (PMID 22238690, 2012). "Blocking this specific PKC could prevent the down-regulation of Foxa1 in human NAFL which, in turn, could help not only reduce intracellular lipids, but alleviate insulin resistance in humans." (PMID 22238690, 2012). "Moreover as Foxa1 is repressed in NAFL, its pharmacological activation could counteract lipid deposition, and could prove useful for the therapy and prevention of NAFLD and insulin resistance." (PMID 22238690, 2012).
invasive carcinoma (1 paper, 2009). A carcinoma that is not confined to the epithelium, and has spread to the surrounding stroma. "FOXA1 expression was demonstrated in 42% of invasive carcinomas, while GATA-3 was detected in 48% of the cases." (PMID 19549328, 2009). "FOXA1 was positive (score ≥ 4) in the nuclei of 42% (93 out of 224) of the invasive carcinomas, while GATA-3 was detected in 48% (97 out of 204) of the cases." (PMID 19549328, 2009).
liver cirrhosis (1 paper, 2017). "Our results also uncovered several other TFs that may regulate the process of liver cirrhosis (e.g. FOXA1, RFX5, and ETS1) which are new potential targets for mechanistic studies of liver cirrhosis." (PMID 28355233, 2017).
Lymphatic Metastasis (1 paper, 2022). Transfer of a neoplasm from its primary site to lymph nodes or to distant parts of the body by way of the lymphatic system. "In Kaplan–Meier method, FIGO III-IV disease, lymphatic metastasis, HDAC3 high expression and FOXA1 high expression sighificantly decreased patients’ DFS in the univariate analysis (p < 0.001, = 0.001, < 0.001 and = 0.001, respectively)." (PMID 34991620, 2022).